RASSF2 (Ras association domain family member 2)
Description:
Potential tumor suppressor. Acts as a KRAS-specific effector protein. May promote apoptosis and cell cycle arrest. Stabilizes STK3/MST2 by protecting it from proteasomal degradation.
Synonyms: CENP-34; KIAA0168; RASFADIN
Tractability: Antibody: its Gene Ontology location is reachable by antibodies, with high confidence. PROTAC: ubiquitination databases record sites on it; its protein half-life has been measured.
Gene: Protein-coding gene on chromosome 20 (4,780,019 to 4,823,870, reverse strand). Ensembl gene ENSG00000101265.
Subcellular location: Nucleus; Cytoplasm; Chromosome, centromere, kinetochore
Subcellular location (Human Protein Atlas): Nucleoplasm; Cytosol; Golgi apparatus; Plasma membrane
Gene Ontology:
Molecular function: protein binding; protein kinase activity
Biological process: negative regulation of peptidyl-serine phosphorylation; positive regulation of apoptotic process; positive regulation of JNK cascade; positive regulation of protein autophosphorylation; positive regulation of protein kinase activity; protein stabilization; regulation of non-canonical NF-kappaB signal transduction; signal transduction
Cellular component: cytoplasm; cytosol; kinetochore; nucleoplasm; nucleus; protein-containing complex
Genetic constraint (gnomAD): Loss-of-function variants: 34 observed, 45.67 expected, observed/expected ratio (o/e) 0.74, 90% interval 0.56 to 0.99. The upper end of that interval is the gene's LOEUF score, 0.99, which puts it in group 4 of 6, group 1 being the genes least tolerant of losing a copy. Missense variants: 364 observed, 429.34 expected, observed/expected ratio (o/e) 0.85, 90% interval 0.78 to 0.93. Synonymous variants: 158 observed, 157.58 expected, observed/expected ratio (o/e) 1, 90% interval 0.88 to 1.14.
Homologues: Orthologues: chimpanzee RASSF2 (99% identical), macaque RASSF2 (98% identical), guinea pig RASSF2 (97% identical), pig RASSF2 (96% identical), dog RASSF2 (96% identical), rabbit RASSF2 (94% identical), rat Rassf2 (93% identical), mouse Rassf2 (93% identical), zebrafish rassf2a (63% identical), zebrafish rassf2b (50% identical), Drosophila melanogaster Rassf (32% identical). Paralogues in human: RASSF4 (56% identical), RASSF6 (39% identical), RASSF5 (20% identical), RASSF1 (17% identical), RASSF3 (15% identical).
Diseases named in the same sentence as RASSF2 in open-access papers:
RASSF2 is named in the same sentence as 59 diseases in open-access papers, as found by Europe PMC text mining. Sharing a sentence is not in itself a finding about the gene and the disease. The quoted sentences say what the papers report.
colorectal cancer (8 papers, 2005 to 2022). A primary or metastatic malignant neoplasm that affects the colon or rectum. "In colorectal cancer, RASSF2 hypermethylation is associated with K-RAS mutations, which are essential in the progression of microsatellite-stable tumors." (PMID 26284587, 2015). "Previously we had also demonstrated that inactivation of RASSF2 by promoter hypermethylation inversely correlates with K-Ras mutation status in colorectal carcinomas." (PMID 19570220, 2009). "Promoter hypermethylation of the RASSF1A and RASSF2 genes has been described in colorectal cancers in 15–45% and 42–70% of cases, respectively." (PMID 34885067, 2021). "It has been reported that primary colorectal cancers, which showed KRAS or BRAF mutations, also frequently showed RASSF2 methylation, and inactivation of RASSF2 enhanced KRAS-induced oncogenic transformation." (PMID 20920251, 2010). "On the contrary, MEK/ERK inhibitor Ras Association Domain Family Member 2 (RASSF2) is targeted by miR-200a, miR-200c, miR-141 in colorectal cancer, and Ras Association Domain-Containing Protein 8 (RASSF8) by miR-429 in non-small lung carcinoma which results in increased proliferation." (PMID 36158660, 2022). "Survival analysis reveals that the low RASSF2 mRNA expression (possibly due to hypermethylation of the RASSF2 promoter) predicts significant worse overall survival in 438 patients with colon cancer (p score: 0.038, expression of RASSF2 in colorectal cancer-The Human Protein Atlas)." (PMID 34885067, 2021). "It has been suggested that aberrant methylation of RASSF2 in plasma of colorectal cancer patients may serve as a cancer biomarker." (PMID 20920251, 2010). "Results suggest a gradual expansion of methylation across CpG islands in MGMT, RASSF2, and SFRP2 promoters during colorectal cancer progression and highlighted their potential role as biomarkers for diagnosis and disease prediction for specific cancer types." (PMID 27095449, 2016). "They identified the RASSF2 promoter region and showed that absence of RASSF2 transcription was caused by DNA methylation, not by alteration of transcription factors, and also showed histone acetylation at the 5′ region of RASSF2 in colorectal cancer cell lines with DNA methylation." (PMID 16265349, 2005).
breast carcinoma (7 papers, 2013 to 2021). "RASSF2 was reported to be associated with ovarian endometriosis, breast cancer, gastric cancer, and childhood acute lymphoblastic leukemia and has been proposed as a novel methylation marker for screening several cancers." (PMID 31552087, 2019). "RASSF2 has been reported as a tumor suppressor to be frequently inactivated by promoter methylation in breast cancer and to inhibit the growth of breast cancer cell lines both in vitro and in vivo." (PMID 34604090, 2021). "Our objectives were to analyze the presence of methylation of the less-studied RASSF2 gene in breast cancer subtypes, along with the well-known gene RASSF1, and to evaluate the prognostic role of these alterations in patients." (PMID 26284587, 2015). "The cause of the clear association between RASSF2 hypermethylation and luminal subtype remains to be determined, since the role of RAS signaling in the various subtypes of breast cancer has been little studied to date." (PMID 26284587, 2015). "RASSF2 was described as being a new putative tumor suppressor gene, given its role in growth inhibition, inactivated by hypermethylation in breast cancer." (PMID 26284587, 2015). "Therefore, more studies in larger cohorts on the clinical involvement of RASSF2 in breast cancer should be performed." (PMID 34604090, 2021). "Four genes AQP1, LFNG, RASSF2 and WWP2 were reported to be associated with breast cancer." (PMID 31640538, 2019). "RASSF2 is another member of the RASSF family that has been little studied in breast cancer." (PMID 26284587, 2015). "Breast cancer cell lines were treated with the demethylating agent 5-aza-2′-deoxycytidine (5-azadC) to study the effect of restoring RASSF2 expression by lentivector technology on cell proliferation and the response to treatment in luminal and triple-negative breast cancer cell lines." (PMID 26284587, 2015). "Bex2 has a significant role in promoting cell survival and growth in breast cancer cells, and Rassf2 might function as a tumor suppressor gene in in vitro cell migration and cell cycle progression." (PMID 23555558, 2013). "As for the three protective genes, the prognostic value of FERMT3 and RASSF2 has been noted in breast cancer, while that of RASSF5 has not." (PMID 34604090, 2021). "In conclusion, RASSF2 gene is differently methylated in luminal and non-luminal tumors and is a promising suppressor gene with clinical involvement in breast cancer." (PMID 26284587, 2015). "RASSF2 is a gene that is hypermethylated in breast cancer and whose clinical value has not been previously studied." (PMID 26284587, 2015). "It would be interesting to investigate whether RASSF2 hypermethylation is related to alterations in the PIK3CA pathway, since PIK3CA and RAS are pathways with apparently mutually exclusive alterations in breast cancer." (PMID 26284587, 2015).
gastric cancer (7 papers, 2005 to 2022). A primary or metastatic malignant neoplasm involving the stomach. "In the present study, we have showed that RASSF2 methylation is frequent in gastric cancer, despite the rarity of K-ras/BRAF mutations in this tumour." (PMID 16265349, 2005). "Results in gastric cancer cell lines suggest that hypermethylation near the transcription start site was associated with loss of RASSF2 mRNA expression, although other mechanisms might also contribute to RASSF2 silencing." (PMID 16265349, 2005). "The role of RASSF2 hypermethylation in predicting poor outcome has been described in cervical and gastric cancer." (PMID 25621889, 2015). "A study on gastric cancer suggested that RASSF2 not only suppressed tumor growth directly but also inhibited inflammation and angiogenesis by inhibiting the Ras-signaling pathway." (PMID 25298284, 2014). "Gastric cancers with methylation at U1 and D1, a change critical for RASSF2 silencing, exhibited significantly less frequent lymphatic permeation than unmethylated gastric cancers." (PMID 16265349, 2005). "We thus showed that RASSF2 is silenced by hypermethylation near the transcription start site in gastric cancer." (PMID 16265349, 2005). "In the present study, we examined the methylation status of RASSF2 at multiple regions which included the CpG island and spanned the transcription start site in gastric cancer cell lines, as well as primary gastric cancers and corresponding non-neoplastic gastric epithelia." (PMID 16265349, 2005). "The results showed that the methylation of SDC2, SFRP2, TERT, and RASSF2 has a certain sensitivity and high specificity in GC screening, which is a potential fecal biomarker of gastric cancer." (PMID 35309131, 2022). "The sensitivity and specificity of a single marker for gastric cancer detection in the training set for SDC2 were 40.9 and 93.3%, for TERT were 36.4 and 90.0%, for RASSF2 were 31.8 and 93.3%, for SFRP2 were 22.7 and 90.0%, and for Hb were 27.3 and 90.0%." (PMID 35309131, 2022). "In primary gastric cancers and corresponding non-neoplastic gastric epithelia, frequencies of RASSF2 methylation ranged from 29% (23 out of 78) to 79% (62 out of 78) and 3% (two out of 78) to 60% (47 out of 78), respectively, at different CpG sites examined." (PMID 16265349, 2005). "We examined methylation status in multiple regions which included the CpG island and spanned the transcription start site of RASSF2 in 10 gastric cancer cell lines, as well as 78 primary gastric cancers and corresponding non-neoplastic gastric epithelia." (PMID 16265349, 2005). "The regions critical for methylation silencing of RASSF2 mRNA expression were examined by analyses of cell lines, while methylation spreading near the RASSF2 transcription start site was examined by analyses of primary gastric cancers and corresponding non-neoplastic gastric epithelia." (PMID 16265349, 2005).
lung carcinoma (6 papers, 2009 to 2017). "Taken together, these data suggests that loss of RASSF2 expression confers a more aggressive phenotype to lung cancer cells." (PMID 22693671, 2012). "Loss of RASSF2 expression also confers resistance to taxol and cisplatin, two frontline therapeutics for the treatment of lung cancer." (PMID 22693671, 2012). "K-Ras is frequently mutated in lung cancer, and inactivation of RASSF2 enhances the transforming potential of K-Ras in rat kidney cells." (PMID 22693671, 2012). "Loss of RASSF2 expression in lung cancer cells dramatically enhanced the transformed phenotype, decreased cell adhesion, and increased invasion." (PMID 22693671, 2012). "In summary, we found that loss of RASSF2 expression enhances the transformed phenotype of lung cancer cells expressing oncogenic K-Ras." (PMID 22693671, 2012). "Moreover, H441 lung cancer cells harbor a mutant K-Ras, and loss of RASSF2 expression in these cells dramatically enhanced their transformed phenotype." (PMID 22693671, 2012). "We adopted an RNAi approach to determine the effects of inactivation of RASSF2 on the transformed phenotype of lung cancer cells containing an oncogenic K-Ras." (PMID 22693671, 2012). "RASSF2 is frequently downregulated in lung cancer with inactivation of RASSF2 being more prevalent in NSCLC than SCLC." (PMID 22693671, 2012). "To confirm that RASSF2 and K-Ras can form an endogenous complex, we serum-starved then briefly serum-stimulated H441 lung cancer cells that express mutant K-Ras and retain RASSF2 expression." (PMID 22693671, 2012). "To determine the biological effects of downregulating RASSF2, we used two independent RASSF2 shRNA constructs to generate stable RASSF2 knockdown cell lines in H441 lung cancer cells." (PMID 22693671, 2012). "Further analysis confirmed that endogenous C1QBP could be immunoprecipitated with endogenous RASSF2 from H441 lung cancer cells, which contain an activated Ras, suggesting the interaction is physiologically relevant." (PMID 26999212, 2016). "In this study, these treatments did not significantly influence in vitro cell survival with respect to the presence or absence of RASSF2 expression, in contrast to the positive effect of RASSF2 expression on the response to the regimen based on taxol and cisplatin in lung cancer." (PMID 26284587, 2015). "Inactivation of RASSF2 also confers resistance to cisplatin and taxol, suggesting that RASSF2, or the signaling pathways that it regulates, may serve as a target for therapy for lung cancer." (PMID 22693671, 2012). "Furthermore, inactivation of RASSF2 conferred resistance to taxol and cisplatin, suggesting that RASSF2 may be a target for epigenetic therapy in lung cancer." (PMID 22693671, 2012). "Thus we have shown that inactivation of RASSF2, a process that occurs frequently in primary tumors, enhances the transforming potential of activated K-Ras and our data suggests that RASSF2 may be a novel candidate for epigenetic-based therapy in lung cancer." (PMID 22693671, 2012). "To determine whether the more aggressive phenotype of the RASSF2 knockdown cells altered their response to chemotherapeutic agents, we treated the cells with taxol or cisplatin, two drugs commonly used in the treatment of nonsmall cell lung cancer, and measured their effects on cell death." (PMID 22693671, 2012). "RASSF2 (RAS association domain family 2) is a negative effector of Ras and has been implicated as a tumor suppressor gene in a number of other forms of epithelial cancer, such as colon, gastric, breast, and lung carcinoma." (PMID 19781100, 2009).
neuroblastoma (4 papers, 2012 to 2023). Neuroblastoma (NB) is the most common solid, extracranial childhood tumor. "Calcipotriol, while reducing neuroblastoma cell proliferation and survival through vitamin D receptor signaling, also regulates cell migration by inducing RASSF2-dependent muting of the Hippo signaling pathway and Hippo pathway effectors (e.g., YAP and TAZ)." (PMID 38249515, 2023). "In the current study, we found that several of the RASSF family genes (RASSF2, RASSF4, RASSF5, RASSF6, RASSF7, and RASSF10) to various degrees were methylated in neuroblastoma cell lines and primary tumors." (PMID 22695170, 2012). "In the disease association analysis (neoplasms, cancer or viral infections, breast neoplasms, neuroblastoma), the LMO3, MYB and BIRC3 oncogenes were also significantly upregulated whereas the WISP2, IGFBP5 and RASSF2 tumour suppressor genes were significantly downregulated in FFs compared to NFs." (PMID 28717200, 2017).
adenoma (3 papers, 2007 to 2023). A neoplasm arising from the epithelium. "To elucidate the differences in the contribution of the Ras signalling pathway to neoplastic development according to colonic sites, we next investigated locational distribution of adenomas with either K-ras/BRAF mutations or RASSF2 methylation, or both." (PMID 17923875, 2007). "Our results suggested that K-ras/BRAF mutations and RASSF2 methylation can cooperate and work synergistically in adenomas." (PMID 17923875, 2007). "Patients who had at least one adenoma carrying either K-ras/BRAF mutations or RASSF2 methylation or both were significantly older than those who had adenoma(s) without these alterations (70 vs 62 years, P=0.01)." (PMID 17923875, 2007). "Adenomas with RASSF2 methylation often carried K-ras/BRAF mutations simultaneously (22 out of 30, P<0.01)." (PMID 17923875, 2007). "Alternatively, however, a specific synergistic correlation between BRAF mutation and RASSF2 methylation may function in Ras signalling disorders during the progression of serrated adenomas." (PMID 17923875, 2007). "There was a locational imbalance among K-ras/BRAF mutations or RASSF2 methylation in adenomas." (PMID 17923875, 2007). "Adenomas with RASSF2 methylation were more likely to carry K-ras/BRAF mutations than those without RASSF2 methylation (73 vs 30%, P<0.01), suggesting that these genetic and epigenetic alterations are mutually correlated and may work synergistically." (PMID 17923875, 2007). "Then, to identify factors for the concomitance of K-ras/BRAF mutations and RASSF2 methylation in adenomas, univariate and multivariate logistic regression analyses were performed with parameters including gender, age, location, morphology, size, and histological diagnosis." (PMID 17923875, 2007). "Adenomas with either K-ras/BRAF mutations, RASSF2 methylation, or both were more frequently observed in the rectum than in the distal colon (65 vs 37%, P=0.04; and 26 vs 6%, P=0.03, respectively)." (PMID 17923875, 2007). "We found that RASSF2 methylation was, like K-ras/BRAF mutations, frequently observed in large adenomas and in serrated adenomas." (PMID 17923875, 2007). "On the other hand, reports regarding the frequency of RASSF1 and RASSF2 methylation in adenomas have been scarce." (PMID 17923875, 2007). "RASSF2 methylation was significantly more frequently observed in large adenomas (⩾2 cm) than in adenomas of 1–2 cm (37 vs 19%, P=0.046)." (PMID 17923875, 2007). "Of the 120 adenomas examined, RASSF2 methylation was observed in 30 (25%) cases, while only 3 (2.5%) adenomas exhibited RASSF1 methylation." (PMID 17923875, 2007). "Consequently, serrated adenomas were likely to have both K-ras/BRAF mutations and RASSF2 methylation (5 out of 8, 63%), despite relatively dispersed locational distribution." (PMID 17923875, 2007). "Some adenomas in the proximal colon carried neither K-ras/BRAF mutations nor RASSF2 methylation, while there were few cancers without these alterations." (PMID 17923875, 2007). "In addition, 2 out of 3 adenomas with RASSF1 methylation also showed methylation of RASSF2." (PMID 17923875, 2007). "In addition, most of serrated adenomas carried RASSF2 methylation (6 out of 8, 75%)." (PMID 17923875, 2007). "Thus, characteristics of adenomas in each patient were not always the same regarding K-ras/BRAF mutations or RASSF2 methylation." (PMID 17923875, 2007). "In addition, clinicopathological features of colorectal tumours that carry the methylation of either RASSF1 or RASSF2 are still largely unknown in adenomas as well as in cancers." (PMID 17923875, 2007). "In 18 patients harbouring plural adenomas, 2 patients each carried two adenomas with K-ras/BRAF mutations, while no patients had two or more adenomas with RASSF2 methylation." (PMID 17923875, 2007).
adenoma (continued). "In addition, in only 4 out of 18 (22%) patients, all of adenomas that each patient carried exhibited the same K-ras/BRAF and RASSF2 status (all exhibited neither K-ras/BRAF mutation nor RASSF2 methylation)." (PMID 17923875, 2007).